TMED3 (transmembrane p24 trafficking protein 3)
Description:
Potential role in vesicular protein trafficking, mainly in the early secretory pathway. Contributes to the coupled localization of TMED2 and TMED10 in the cis-Golgi network.
Synonyms: p24gamma4; C15orf22; p24B; p24g4; p26
Tractability: Antibody: UniProt predicts a signal peptide or a membrane-spanning region. PROTAC: ubiquitination databases record sites on it; its protein half-life has been measured.
Gene: Protein-coding gene on chromosome 15 (79,311,109 to 79,427,432, forward strand). Ensembl gene ENSG00000166557.
Subcellular location: Endoplasmic reticulum-Golgi intermediate compartment membrane; Golgi apparatus, cis-Golgi network membrane; Golgi apparatus, Golgi stack membrane; Endoplasmic reticulum membrane; Cytoplasmic vesicle, COPI-coated vesicle membrane
Subcellular location (Human Protein Atlas): Golgi apparatus
Pathways (Reactome):
Vesicle-mediated transport: COPI-dependent Golgi-to-ER retrograde traffic; COPI-mediated anterograde transport
Gene Ontology:
Biological process: endoplasmic reticulum to Golgi vesicle-mediated transport; Golgi organization
Cellular component: endoplasmic reticulum; endoplasmic reticulum membrane; endoplasmic reticulum-Golgi intermediate compartment; endoplasmic reticulum-Golgi intermediate compartment membrane; Golgi apparatus; COPI vesicle coat; Golgi membrane; transport vesicle; COPI-coated vesicle membrane; Golgi cisterna membrane
Genetic constraint (gnomAD): Loss-of-function variants: 13 observed, 21.11 expected, observed/expected ratio (o/e) 0.62, 90% interval 0.4 to 0.98. The upper end of that interval is the gene's LOEUF score, 0.98, which puts it in group 4 of 6, group 1 being the genes least tolerant of losing a copy. Missense variants: 267 observed, 285.04 expected, observed/expected ratio (o/e) 0.94, 90% interval 0.85 to 1.04. Synonymous variants: 117 observed, 126.59 expected, observed/expected ratio (o/e) 0.92, 90% interval 0.8 to 1.08.
Homologues: Orthologues: macaque TMED3 (97% identical), chimpanzee TMED3 (93% identical), rat Tmed3 (93% identical), pig TMED3 (93% identical), mouse Tmed3 (90% identical), guinea pig TMED3 (88% identical), dog TMED3 (88% identical), rabbit TMED3 (78% identical), zebrafish tmed3 (59% identical), Drosophila melanogaster p24-1 (41% identical), Caenorhabditis elegans tmed-12 (13% identical). Paralogues in human: TMED7 (65% identical), TMED1 (32% identical), TMED5 (29% identical), TMED2 (28% identical), TMED4 (24% identical), TMED9 (24% identical), TMED10 (18% identical), TMED6 (18% identical).
Diseases named in the same sentence as TMED3 in open-access papers:
TMED3 is named in the same sentence as 29 diseases in open-access papers, as found by Europe PMC text mining. Sharing a sentence is not in itself a finding about the gene and the disease. The quoted sentences say what the papers report.
colon cancer (12 papers, 2014 to 2025). "TMED3 is an emerging tumor suppressor gene implicated in prostate cancer, colon cancer and hepatocellular carcinoma progression." (PMID 28797121, 2017). "In contrast, TMED3 was identified as a tumor suppressor in colon cancer and proposed to inhibit metastasis by repressing TMED9." (PMID 33888099, 2021). "In fact, TMED3 was recovered from a genome-wide in vivo screen for metastatic suppressors in human colon cancer." (PMID 31878985, 2019). "Transmembrane p24 trafficking protein 3 (TMED3) is a metastatic suppressor in colon cancer and hepatocellular carcinoma." (PMID 31057605, 2019). "We propose that antagonistic secretion-transcription loops gated by TMED9 and TMED3 represent a key modulatory network for the control of the number of colon cancer metastatic cells." (PMID 31253868, 2019). "This anti-metastatic role of WNT-TCF signaling is consistent with the in vivo, unbiased identification of the positive WNT-TCF modulator TMED3 as an endogenous suppressor of distant colon cancer metastases." (PMID 31253868, 2019). "We propose that primary colon cancer cells can transition between two states characterized by secretion-transcription regulatory loops gated by TMED3 and TMED9 that modulate their metastatic proclivities." (PMID 31253868, 2019). "Knockdown (kd) of TMED3 was achieved in CC14 primary human colon cancer cells, which are E1554->frameshift APC mutant, using a previously validated specific short-hairpin RNA (shTMED3 with kd of 95%)." (PMID 31253868, 2019). "For example, TMED3 can promote anti-metastatic WNT signaling in colon cancer cells, whereas it has been reported to promote IL11 signaling and tumor progression in liver cancer cells." (PMID 31253868, 2019). "Using a novel in vivo assay to identify metastatic suppressor functions, we have uncovered that SOX12 and TMED3 limit the metastatic spread and/or growth of human colon cancer cells in mice." (PMID 24920608, 2014). "Thus, TMED9 functions as an oncogene in colon cancer, and the malignant properties of TMED3 are cell-type specific." (PMID 37928880, 2023). "TMED9 was more than two-fold increased when TMED3 was knocked down in colon cancer cells." (PMID 37928880, 2023). "TMED9 antagonizes TMED3 function through promoting colon cancer metastases." (PMID 35805075, 2022). "TMED9 and TMED3 play a role in this metastatic transition with their activities that balance each other to determine metastatic outcomes of colon cancer cells and control, in opposite manners, a global gene cohort that includes multiple factors implicated in the regulation of metastases." (PMID 35805075, 2022). "TMED3 was initially found to be a metastatic inhibitory factor for colon cancer." (PMID 34838013, 2021). "Opposite roles of TMED9 and TMED3 in regulating the progression of colon cancer were reported." (PMID 33888099, 2021). "For instance, TMED3 was initially found to be a metastatic inhibitory factor for colon cancer." (PMID 34838013, 2021). "To elucidate how blockade of TMED3 promotes pro-metastatic states in primary colon cancer cells, we first investigated if it could affect the expression of other TMED family members." (PMID 31253868, 2019). "When TMED3 was knocked down in colon cancer cells, TMED9 was upregulated more than twofold." (PMID 31878985, 2019). "Transmembrane p24 trafficking protein 3(TMED3) is a metastatic suppressor in colon cancer, but its function in the progression of hepatocellular carcinoma (HCC) is unknown." (PMID 27901021, 2016). "However, TMED3 was also reported as a metastatic suppressor and knocking down TMED3 could promote metastatic growth in human colon cancer." (PMID 35854294, 2022). "Further, TMED3 may contribute to the progression of colon cancer." (PMID 31057605, 2019). "However, although TMED3 seems oncogenic in hepatocellular carcinomas, renal cell carcinomas, prostate cancers and breast cancers, it appears to have tumour suppressor properties in human colon cancers." (PMID 31878985, 2019).
colon cancer (continued). "Lastly, TMED9 was shown to mediate colon cancer metastases by activating the GLI1, CNIH4 and TGFA regulatory pathway and opposing TMED3-WNT-TCF signaling." (PMID 40497947, 2025). "In summary, TMED3 positively modulates WNT-TCF signaling, which suppresses the metastatic potential of colon cancer cells." (PMID 35805075, 2022). "Although the roles of TMED9 and TMED3 in HCC differed from those in colon cancer, how the interaction between TMED9 and TMED3 promotes HCC progression remains for further evaluation." (PMID 33888099, 2021). "In flies and mammals, specific TMED proteins control WNT secretion, and both TMED3 and WNT-TCF signaling act as metastatic suppressors in human colon cancer cells." (PMID 31253868, 2019). "A previous unbiased in vivo RNAi screen revealed TMED3 as a positive modulator of WNT signaling and blocking WNT-TCF signaling with dnTCF has been shown to promote metastases from multiple primary colon cancer cells." (PMID 31253868, 2019). "A previous genome-wide RNAi screen uncovered colon cancer metastatic suppressor and WNT promoting functions of TMED3, a member of the p24 ER-to-Golgi protein secretion family." (PMID 31253868, 2019). "To extend the findings in CC14 cells with TMED3 and SOX12 presented above, we used HT29 human colon cancer cells to test the effects of shTMED3 and shSOX12." (PMID 24920608, 2014). "Our present results define novel functions of the TMED3 and SOX12 genes as in vivo suppressors of human colon cancer metastases in mice." (PMID 24920608, 2014). "Therefore, TMED3, being a positive regulator of canonical WNT-TCF signaling, acts as a suppressor of colon cancer metastases." (PMID 35805075, 2022). "Moreover, TMED3 silencing induces the down-regulation of WNT-TCF target genes involved in colon and colon cancer stemness, including ASCL2 and LGR5." (PMID 35805075, 2022). "Consistent with non-redundant functions in animals, we have only identified TMED3 even though we have detected all TMED mRNAs except that for TMED10 in the human colon cancer cells used (data not shown)." (PMID 24920608, 2014). "To test whether TMED3 KD modifies intracellular WNT localization, we chose to analyze the localization of exogenous WNT1, a WNT gene product that is expressed in colon cancer." (PMID 24920608, 2014). "Indeed, whereas both the KD of SOX12 and TMED3 are effective in CC14 (with undetermined APC status in this non-clonal primary colon cancer cell population), TMED3 KD has diminished potency in comparison with KD of SOX12 in HT29." (PMID 24920608, 2014). "Although the homolog of TMED3 in Drosophila (logjam; Strating & Martens, 2009) may not be involved in Wnt signaling, we tested for this possibility in human colon cancer cells since p24 proteins are multifunctional and TMED5 affects WNT1 secretion in 293T cells." (PMID 24920608, 2014). "Colon cancers express multiple canonical and non-canonical WNT genes, and it is not clear what degree of specificity may TMED3 harbor for the different human WNT proteins." (PMID 24920608, 2014).
breast carcinoma (9 papers, 2019 to 2025). "TMED3 expression levels were substantially linked with clinicopathological characteristics in breast cancer patients and predicted a poor outcome." (PMID 37928880, 2023). "Accumulating evidence shows that TMED3 is a newly identified cancer-related protein in several malignancies, such as breast cancer, gastric cancer, chordoma, and lung cancer." (PMID 39735675, 2025). "TMED3 knockdown prevented the proliferation, migration, invasion, and cell cycle advancement that TMED3 overexpression induced in breast cancer cell lines as compared to controls." (PMID 37928880, 2023). "TMED3 has also been demonstrated to facilitate breast cancer cell migration and proliferation through Wnt/-catenin signaling." (PMID 37928880, 2023). "The oncogenic role of TMED3 was also verified in breast cancer development through clinicopathological data and in vitro and vivo experiments." (PMID 35854294, 2022). "TMED3 expression is strongly up-regulated in several cancer types (including osteosarcoma, breast cancer, chordoma, HCC and non-small cell lung cancer (NSCLC)) and correlates with poor prognosis in patients." (PMID 35805075, 2022). "In breast cancer cells, the elevated expression level of TMED3 was significantly correlated with the level of estrogen receptor, progesterone receptor and human epidermal growth factor receptor-2, as well as the status of lymph nodes metastasis." (PMID 35854294, 2022). "In consistence with our study, knocking down TMED3 in breast cancer cell models dramatically limited cell colony formation and cell motility by Wnt/β-catenin signaling." (PMID 35854294, 2022). "TMED3 enhances breast cancer cell proliferation by stimulating the Wnt/β-catenin cascade, which causes an increased expression of relevant cell cycle proteins, including CDK4, c-myc and cyclinD1." (PMID 35805075, 2022). "TMED3 was also reported to promote proliferation and motility of breast cancer cells by activating WNT/β-catenin pathway." (PMID 33888099, 2021). "In cell culture, TMED3 promotes the proliferation, migration and invasion of breast cancer cells, MCF-7 and MDA-MB-231." (PMID 31878985, 2019). "An example of a non-canonical MHC-bound peptide from a cancer-relevant gene is an 11 aa-long MHC bound peptide (binding affinity 8.91 nM) from a downstream ncORF in TMED3, an upregulated gene in breast cancer promoting proliferation, migration, and invasion of breast cancer cells." (PMID 37275273, 2023). "Similarly, TMED3 promotes breast cancer cell migration and invasion by activating the Wnt/β-catenin signaling cascade." (PMID 35805075, 2022). "TMED3 was reported to be an oncoprotein in HCC, prostate cancers, breast cancers, and kidney cancers." (PMID 33888099, 2021).
hepatocellular carcinoma (9 papers, 2016 to 2025). A malignant tumor that arises from hepatocytes. "Contrarily, low expression of TMED3 prevented hepatocellular carcinoma cells from migrating, whereas overexpression of TMED3 increased cell viability." (PMID 37928880, 2023). "In regarding to the downstream of TMED3 in tumor, a previous study proposed that TMED3 promoted metastasis of hepatocellular carcinoma and served as a contributor in tumor progression via IL-11/STAT3 signaling pathway." (PMID 35854294, 2022). "In fact, TMED3 knockdown inhibited hepatocellular carcinoma cell migration, whereas TMED3 overexpression enhanced cell motility." (PMID 31878985, 2019). "TMED3-mediated IL-11/STAT3 signaling pathway activation was recently reported to participate in tumor progression in hepatocellular carcinoma." (PMID 29100303, 2017). "Furthermore, TMED3 overexpression was significantly correlated with poor prognosis in patients with hepatocellular carcinoma and clear cell renal cell carcinoma." (PMID 36991473, 2023). "In addition, TMED3 expression is upregulated in human hepatocellular carcinoma tissues." (PMID 31878985, 2019).
prostate carcinoma (8 papers, 2012 to 2025). A carcinoma that arises from epithelial cells of the prostate gland. "To investigate the potential molecular mechanism underlying the role of TMED3 in prostate cancer, we used the TCGA database." (PMID 39735675, 2025). "The IHC results showed that TMED3-downregulated mice exhibited a lower percentage of Ki67+ tumor cells than did mice in the shCtrl group, which implied that TMED3 was associated with the modulatory process of apoptosis in prostate cancer." (PMID 39735675, 2025). "High TMED3 expression resulted in the loss of function of FOXO1a and FOXO3a owing to S249 phosphorylation, thereby promoting prostate cancer development." (PMID 39735675, 2025). "Herein, we compared TMED3 protein levels between normal human prostate cells and prostate cancer cells and found its higher levels in prostate cancer cells than in normal cells." (PMID 39735675, 2025). "In vivo, TMED3 downregulation suppressed the apoptosis, growth, and metastasis of prostate cancer cells via FOXO1a and FOXO3a." (PMID 39735675, 2025). "CCK-8 and FCM assays were performed to investigate the effect of TMED3 inhibition on prostate cancer cell growth." (PMID 39735675, 2025). "Herein, initially, we examined the proliferation, migration, invasion, and apoptosis of prostate cancer cells after knocking down TMED3 in vitro." (PMID 39735675, 2025). "The in vivo results showed that TMED3 downregulation suppressed the apoptosis of prostate tumor cells and alleviated prostate cancer." (PMID 39735675, 2025). "High-throughput transcriptomics and RNAi analysis in a previous study showed that the mRNA expression of ERGIC1 and TMED3 was upregulated in cultured prostate cancer cells." (PMID 39735675, 2025). "The in vitro results showed that TMED3 knockdown in prostate cancer cells inhibited the proliferation, migration, and invasion and promoted the apoptosis of prostate cancer cells." (PMID 39735675, 2025). "Herein, the KEGG pathway enrichment analysis was performed to investigate the possible downstream cooperator of TMED3 in prostate cancer, and a strong correlation between TMED3 and FOXO signaling pathway phosphorylation was observed." (PMID 39735675, 2025). "The in vivo experiments showed that TMED3 downregulation suppressed prostate cancer progression in mice." (PMID 39735675, 2025). "Additional experiments confirmed that the TMED3-induced phosphorylation of FOXO1a and FOXO3a played a role in prostate cancer progression." (PMID 39735675, 2025). "Based on this mouse model of prostate cancer, we confirmed that TMED3 downregulation decreased p-FOXO1a and p-FOXO3a levels rather than FOXO1a and FOXO3a levels." (PMID 39735675, 2025). "Thus, in the present study, we hypothesize that the TMED3-induced phosphorylation of FOXO1a and FOXO3a may modulate the proliferation, migration, invasion, and apoptosis of prostate cancer cells, thereby causing prostate cancer." (PMID 39735675, 2025). "Among them, the FOXO pathway plays a protective role in prostate cancer, and a strong correlation was observed between TMED3 and the FOXO pathway." (PMID 39735675, 2025). "For instance, TMED3 was highly expressed in prostate cancer and metastatic prostate cancer, and high expression of TMED3 was associated with the expression of the androgen receptor and ERG oncogene." (PMID 36991473, 2023). "Because TMED3 was abnormally elevated in tumor samples from prostate cancer patients, it has also been identified as a potential drug target." (PMID 35754792, 2022). "TMED3 was also identified as a potential drug target for prostate cancer since it is elevated in patient tumour samples." (PMID 31878985, 2019). "AIM1, ERGIC1, and TPX2 were shown to be highly expressed especially in prostate cancer tissues, and high mRNA expression of ERGIC1 and TMED3 associated with AR and ERG oncogene expression." (PMID 22761906, 2012).